CD4 (CD4 molecule)
Diseases named in the same sentence as CD4 in open-access papers (continued):
Sharing a sentence is not in itself a finding about the gene and the disease.
COVID-19 (continued). "The presence of SARS-CoV-2 specific CD4+ T cells was associated with effective viral clearance whereas absence of the specific CD4+ T cells against SARS-CoV-2 was linked with severe COVID-19." (PMID 36369012, 2022). "People living with HIV (PLWH) face increased risk for developing severe COVID-19 because the virus causes a deficit in CD4+ and CD8+ T-cells responsible for stimulating the immune system." (PMID 36417259, 2022). "Among PWH, severe COVID-19 breakthrough risk increased with decreasing CD4 cell count (compared with CD4 cell count ≥500 cells/μL)." (PMID 36227594, 2022). "Neutrophils, macrophages, and CD4+T cells in patients with COVID-19 can infiltrate myocardial tissue, causing pathological cardiac remodeling and fibrosis, leading to the development of HF and increased mortality." (PMID 36420258, 2022). "Similar results were obtained using molecular biology methods; in particular, it was shown that the expression of Th17-associated genes decreased in peripheral blood CD4+ T cells of patients with severe COVID-19, as exemplified by RORC, IL17A, IL17F and CCR6." (PMID 35216349, 2022). "Severe forms of COVID-19 have been directly associated with an immune system dysregulation that includes a profound abnormal activation of both CD4+ and CD8+ T cell compartments with a massive release of pro-inflammatory cytokines (cytokine storm)." (PMID 35743021, 2022). "Intriguingly, our data also showed that increased circulating MDSCs in children with acute COVID-19 were associated with decreased percentage of CD4 + T cells but increased percentages of CD8 + T cells and NK cells." (PMID 35733812, 2022). "Data from cilinical studies showed that the loss of CD4+T cells responses were significantly related to disease severity in COVID-19 patients." (PMID 36550578, 2022). "Th-17 cells, a proinflammatory subset of CD4 T lymphocytes, have been suggested as a possible cause of coronavirus disease-19 (COVID-19)-related immunological injuries." (PMID 36349054, 2022). "The strong association of CD4+ macrophages with ALI in COVID-19 prompted us to assess myeloid cell transcriptomes for distinct subsets associated with CD4 expression." (PMID 35446789, 2022). "COVID-19 activates CD4+ T cells to differentiate into pathogenic Th1 cells, which release GM-CSF and other proinflammatory cytokines that further activate monocytes to release IL-6." (PMID 35062368, 2022). "Biopsy of lung samples from patients with COVID-19 showed inflammatory cell clusters, including multinucleated giant cells (MGCs) and CD4+ T lymphocytes, suggesting a possible association with sarcoidosis, which also has MGCs." (PMID 35615369, 2022). "In multivariable analyses among PWH, being female, older, having a cancer diagnosis, and lower CD4 cell count were associated with increased risk of severe breakthrough illness, whereas previous COVID-19 was associated with reduced risk." (PMID 36227594, 2022). "While immunodeficiency is reported as a risk factor for COVID-19, we present a patient with idiopathic CD4+ lymphocytopenia who developed severe COVID-19 with an unexpected clinical course and complete recovery." (PMID 35464498, 2022). "Defective GC formation associated with CD4 T-cell depletion in the lymph nodes of severe COVID-19 patients has been also reported." (PMID 36030261, 2022). "In a multicenter registry-based cohort reported in the USA, PLWH with CD4+ cell count less than 200 cells/μL was associated with increased risk of COVID-19 related mortality and hospitalization compared to those who have higher CD4+ cell count [50••]." (PMID 34843064, 2022). "Persistant infection leads to further T cell exhaustion with lymphopenia with a high CD8+/CD4+ ratio as a major hallmark of progression to severe COVID-19." (PMID 35891232, 2022). "The striking loss of T cells, particularly of naïve CD4 T cells, has been already characterized in COVID-19 patients, though many effector and memory subsets are proportionally increased." (PMID 35407485, 2022).
COVID-19 (continued). "Th-17 cells, a proinflammatory subset of CD4 T lymphocytes, have been suggested to be implicated in the immune-related damage associated with COVID-19." (PMID 36349054, 2022). "Decrease IFN-γ expression in CD4+ T cells has been associated with severe COVID-19 cases in severe reports." (PMID 36094915, 2022). "Purified MDSCs from COVID-19 patients not only caused suppression of both CD4 + and CD8 + T cell proliferation and IFN-γ production, but also induced the production of TGF-β." (PMID 36581679, 2022). "PWH with lower CD4 cell counts (<350 cells/μL), however, had higher risk of severe COVID-19 breakthrough illness compared with PWoH, suggesting a role of immune dysfunction in the increased risk." (PMID 36227594, 2022). "Early induction and antigenic diversity of the SARS-CoV-2-specific T-cell responses is associated with mild COVID-19 and cross reactivity with CD4+ T cell responses to other human coronaviruses are associated with mild infection." (PMID 35014605, 2022). "Reduced frequency of M. tuberculosis-specific CD4+ T cells in peripheral blood was found in patients with COVID-19, suggesting increased susceptibility to progression to active tuberculosis." (PMID 36465947, 2022). "Data coming from sever COVID-19 patients found an damaged function of CD4+T cells, associated with lower IFN-γ secretion." (PMID 36550578, 2022). "The TNF-α, NT-proBNP, albumin-to-globulin ratio, and CD4+ T-cells were also associated with an increased risk of death from COVID-19." (PMID 35453526, 2022). "COVID-19 patients with mild disease severity and rapid viral clearance were associated with rapid induction of CD4+ T cells and vice versa." (PMID 36014958, 2022). "Memory CD8+ responses take up an effector phenotype while circulating memory CCR6+ Tfh cells, which accounted for most circulating CD4+ responses, increased over the eight months and were associated with reduced COVID-19 severity." (PMID 35401519, 2022). "In this study, we found that children with COVID-19 have significantly increased percentages of MDSC that were associated with CD4 + T cell lymphopenia and worse clinical outcomes defined by increased need for respiratory support and prolonged hospitalization." (PMID 35733812, 2022). "Decreased CD3+CD4+ T cell count at the time of hospital admission was closely associated with a poor prognosis of COVID-19 and the development of severe bilateral pneumonia." (PMID 35632823, 2022). "HIV causes immunodepression by depleting CD4 cells, thus reducing the capacity of the organism to defend against bacterial, fungal, parasitic, and viral infections such as COVID-19." (PMID 35031068, 2022). "Compared to antibodies and CD8+T cells, specific CD4+T cells are more strongly associated with reduced COVID-19 severity." (PMID 36420258, 2022). "This is the most likely risk factor for PCP development in this cohort, along with CD4+ lymphopenia, which has been observed in the majority of patients affected by COVID-19 and is associated with a poor prognosis, particularly in younger patients." (PMID 35603769, 2022). "Studies have shown that severe COVID-19 is associated with significant decrease in numbers of CD4+ T cells, CD8+ T cells and B cells." (PMID 35757734, 2022). "This study indicated that a low CD4 count (less than 200 cells/mm3) was associated with COVID-19 severity." (PMID 36192742, 2022). "The increase in HLA-DR and CD38 expression associated with activation of CD8 and CD4 T cells in critical COVID-19 patients has already been found in association with an increased frequency of terminally differentiated EMRA CD4+ and CD8+ cells." (PMID 35425776, 2022). "COVID-19 death was associated with a CD4+ T-cell count of <200 cells/μL at admission and with tuberculosis infection." (PMID 35458478, 2022). "In the subgroup of patients with a compromised immune function (CD4+ T cells < 350/μl), vaccination reduced the risk of COVID-19 by 2·53 times (95% CI 1·40–4·60)." (PMID 35340627, 2022).
COVID-19 (continued). "This body of evidence makes it feasible to think that subjects with a low number of IL-2-producing CD4+ T cells in response to in vitro polyclonal stimuli display increased susceptibility to severe COVID-19 after SARS-CoV-2 infection." (PMID 35860236, 2022). "The 31 severe COVID-19-associated genes that overlapped with the differentially expressed genes in the SARS-Cov-2 M protein-reactive CD4+ TCLs were identified and plotted based on their expression level." (PMID 35844575, 2022). "The combined effect of TB and SARS-CoV-2 infection likely causes a pronounced lymphocytopenia and, consequently, a CD4 + cell decrease as a reliable indicator of the severity of COVID-19." (PMID 36465947, 2022). "This suggests that follicular helper CD4+ T-cell exhaustion is a major factor in causing severe COVID-19 cases and mortality." (PMID 36471834, 2022). "Antibody responses to mRNA, adenovirus vector, and inactivated COVID-19 vaccines all demonstrated that lower CD4 count (<200/μl) or detectable viral loads were the risk factors for lower nAbs levels among PLWH." (PMID 36325346, 2022). "There is also some evidence that HIV-positive individuals with low CD4 counts—including many of those who faced COVID-19-related delays in initiating ART—face a greater risk of mortality if they are infected with COVID-19." (PMID 35361209, 2022). "EBNA1BP2 has been confirmed to be one of the hub genes in COVID-19 susceptibility and was related to the levels of infiltrating immune cells, including CD4+ activated memory T cells, follicular helper T cells and plasma cells." (PMID 36457997, 2022). "An analysis of RNA-seq of 126 COVID-19 patient blood samples from a GEO dataset revealed a strikingly elevated level of m6A modification associated with increased expression of CD4+ T cells in leukocytes of infected compared to uninfected individuals." (PMID 35897696, 2022). "SU was found to increase COVID-19 risk, which was mainly attributed to the modulation of PCs and CD4 TEM." (PMID 34824394, 2021). "By multivariate logistic regression, our results suggested that the decrease in CD4 + T cells was a risk factor for death in COVID-19 patients." (PMID 33711813, 2021). "In our population of PLWHIV, none of the variables linked to HIV infection, including the time of HIV infection, CDC stage, the nadir of CD4 cell counts, current CD4 count, and viral load were associated with COVID-19." (PMID 34946093, 2021). "Some studies have revealed that clonality and skewing of TCR repertoires from COVID-19 patients by next-generation sequencing were associated with severity of diseases, such as early CD4+ and CD8+ T cell activation and interferon type I and III responses." (PMID 35011632, 2021). "Reduced CD4+T and CD8+T cell levels were both associated with in-hospital death, but only decreased CD4+T cell level was an independent predictor for in-hospital death in COVID-19 patients." (PMID 33435865, 2021). "We also performed Cox proportional hazard regression, which showed that only decreased CD4+T cell level was an independent risk for in-hospital death in COVID-19 patients after adjusting for other confounding factors." (PMID 33435865, 2021). "In our cohort of hospitalised COVID-19 patients we showed an independent association between CD4+ T cell subset frequency and disease severity, with reduced CD4+ T cells, Th1 and Tregs showing the strongest relation with a severe clinical presentation." (PMID 34925369, 2021). "In short, the scATAC-seq analysis were indicated an activated and inflammatory state of T cells (especially, CD8+ T cells) during COVID-19, associated with a possibility of the decreased function of CD4+ T cells (i.e., Th1) in the cases of SCPs." (PMID 33717140, 2021). "Further survival analysis revealed that CD4 + T cell counts and neutrophil counts remained significant for the prediction of mortality risk in COVID-19 patients." (PMID 33711813, 2021).
COVID-19 (continued). "In conclusion, a sustained decrease in lymphocyte subsets, especially CD4+ T cells and NK cells, interacting with proinflammatory cytokine storms was associated with severe disease and poor prognosis in COVID-19." (PMID 33461503, 2021). "Both decreased CD4+T and CD8+T cell levels were associated with in-hospital death in COVID-19 patients, but only the reduction of CD4+T cell level was independently associated with increased in-hospital death in COVID-19 patients." (PMID 33435865, 2021). "A sustained decrease in lymphocyte subsets, especially CD4+ T cells and NK cells, interacting with proinflammatory cytokine storms was associated with severe disease and poor prognosis in COVID-19." (PMID 33461503, 2021). "Patients with COVID-19 have been found to have decreased levels of CD4+ T-lymphocytes (< 200 cells/μL), which increases susceptibility for fungal infection development." (PMID 34940403, 2021). "Studies showed that induction of SARS-CoV-2-specific CD4+ T cells was highly associated with a good prognosis in COVID-19 severity." (PMID 34737743, 2021). "The cellular and molecular mechanisms underlying disease severity-dependent virus-specific CD4+ T-cell differentiation in COVID-19 patients warrants further investigations." (PMID 33686064, 2021). "Mass cytometry indicates that there is an increase in the CD4+ T lymphocytes in COVID-19 and associated hematological malignancy, due to an increase in the naïve subpopulation." (PMID 33794925, 2021). "In a “cytokine storm microenvironment,” CD4+ T cells recruit pathogenic Th1 cells, which aid in COVID-19 pathogenesis via macrophage activation." (PMID 34943795, 2021). "Only reduced CD4+T cell level was independently associated with increased in-hospital death in COVID-19 patients." (PMID 33435865, 2021). "The present study demonstrates the association between CD4+ T cell dysregulation and COVID-19 severity and progression." (PMID 34925369, 2021). "By contrast, immune-compromised, HIV-infected individuals with CD4+ T cell counts below 200 cells/mm3 are associated with increased COVID-19 disease severity and mortality." (PMID 34252054, 2021). "The results suggested that depletion of CD4+ cells was associated with the increased risk of progression of COVID-19 in the obesity subgroup." (PMID 33746594, 2021). "Infection, such as with COVID-19, then exacerbates the imbalanced aged immune system, thereby exacerbating the loss of CD4 + T cells and inflammatory macrophage reaction." (PMID 34906189, 2021). "This systematic review and meta-analysis of 28 studies not only analyse the association between HIV and mortality from COVID-19 but evaluate the role of confounding factors such as age, gender, ethnicity, CD4 cell count and ART in this cohort." (PMID 33936793, 2021). "This study concluded that the cytokine storm is associated with COVID-19 severity, likely through increased pulmonary pathology, T cell depletion, and CD4+ T cell dysfunction." (PMID 34185801, 2021). "For example, a reduction in IFN-γ expression has been observed in CD4+ T cells of patients with COVID-19 associated with disease severity." (PMID 34749737, 2021). "The severity of COVID-19 patients has been associated with a skewed CD4+ T cell response to cytotoxic CD4+ T follicular helper (Tfh) cells, reduced regulatory T cells and a less coordinated CD4+ and CD8+ T cell response." (PMID 34858440, 2021). "Factors associated with risk for severe COVID-19 in HIV-1-infected patients were low CD4+ T cell counts and discontinuation of ART." (PMID 34198973, 2021). "Fast induction of CD4+ T cells was related to a milder disease, while defects in inducing SARS-CoV-2-specific CD4+ T cells were associated with severe or fatal COVID-19." (PMID 34434199, 2021). "Of note, we have also shown in SARS-CoV2 patients an increase of Th1 and Th1/Th17 CD4 T cell lineages and a decrease in Th2 cells supporting the inflammatory profile of the T cell response associated with COVID-19." (PMID 34373466, 2021).
COVID-19 (continued). "It would be interesting to follow the dynamics and functions of CD4+ T cell subsets along with application of high-dose IVIg to better understanding the mechanism underlying COVID-19." (PMID 33679771, 2021). "The association between lymphopenia and the severity of COVID-19 implied as the depletion of lymphocytes with had occurred, especially CD4+T and CD8+T cells." (PMID 34222268, 2021). "It was reported that a decrease in the number of T cells—particularly CD4+ T cells—is a hallmark of COVID-19." (PMID 34687295, 2021). "This is consistent with low nadir CD4+ T cell counts being associated with increased mortality in COVID-19 patients." (PMID 34252054, 2021). "Neutrophilia, lymphocytopenia, low CD4+ T cells, and decreased C3 were immunity-related risk factors predicting mortality of patients with COVID-19." (PMID 32746940, 2020). "Old age, comorbidity of malignant tumor, neutrophilia, lymphocytopenia, low CD4+ T cells, decreased C3, and low oximetry saturation were the risk factors of death in patients with confirmed COVID-19." (PMID 32746940, 2020). "Like for HIV, lymphopenia and drastic reduction of CD4+ T cell counts in COVID-19 patients have been linked with poor clinical outcome." (PMID 33384690, 2020). "In the present study, we found that age ≥65 years, CK ≥ 180 U/L, and CD4+ cell counts <300 cells/μL at admission were associated with disease progression during 14 days after hospital admission in patients with milder COVID-19." (PMID 33336038, 2020). "Old age, comorbidity of malignant tumor, neutrophilia, lymphocytopenia, low CD4+ T cells, decreased C3, and low oximetry saturation were positively correlated with the risk of death in patients with COVID-19." (PMID 32746940, 2020). "CD8+ T cells and CD4+/CD8+ ratio showed a significant association with the inflammatory status in COVID-19 and were independent predictors for poor outcomes." (PMID 32962761, 2020). "In contrast,anti-inflammatory genes associated with CD4+ T cellswere downregulated in COVID-19 patients relative to that in the HCs." (PMID 32377375, 2020). "In terms of the relevance of immune cell-associated signaling pathways, TCR signaling in Naïve CD4+/CD8+ T cells was significantly activated in both COVID-19 and IPF groups." (PMID 33264345, 2020). "We observed that age ≥65 years, CK ≥ 180 U/L, and CD4+ T-cell counts <300 cells/μL at admission were risk factors associated with disease progression to severe COVID-19 during 14 days after admission." (PMID 33336038, 2020). "Together, our results provided an evidence showing that decreased number of CD4+ T cells is an immunity-related risk factor predicting death rate of patients with COVID-19." (PMID 32746940, 2020). "It has been reported that CD4+ T cell depletion associated with severe COVID-19 and corticosteroid-based treatments could induce the activation of pulmonary TB in individuals with LTBI." (PMID 40458413, 2025). "Our findings suggest that differences in CD4+ T cell responses between children and adults could underlie observed differences in COVID-19 severity." (PMID 40906527, 2025). "Thus, COVID-19-associated inflammation also reprograms helper CD4+T cells into cytotoxic CD4+T cells, which affects their long-term immune function due to an alteration in their proliferation action." (PMID 41009359, 2025). "Notably, SARS-CoV-2–specific CD4+ T cells demonstrate the strongest association with reduced COVID-19 severity compared to antibody or CD8+ T cell responses." (PMID 41041302, 2025). "Alterations in immune responses associated with viral persistence and severe COVID-19 are at least partially triggered by the infection of CD4+ T helper cells by SARS-CoV-2, as previously reported, leading to T cell death or dysfunctional T cells resulting from inflammatory cytokine storm." (PMID 41346576, 2025).